TXNIP (thioredoxin interacting protein)
Diseases named in the same sentence as TXNIP in open-access papers (continued):
Sharing a sentence is not in itself a finding about the gene and the disease.
Impaired glucose tolerance (3 papers, 2017 to 2021). An abnormal resistance to glucose, i.e., a reduction in the ability to maintain glucose levels in the blood stream within normal limits following oral or intravenous administration of glucose. "TXNIP has been shown to promote GLUT1 and GLUT4 endocytosis and thus negatively regulate glucose uptake, and TXNIP expression has been reported to be increased in muscles from individuals with impaired glucose tolerance or T2D14." (PMID 34795407, 2021). "Therefore, we examined differences in TXNIP DNA methylation and expression in the 23 offspring with abnormal glucose tolerance (impaired fasting glucose IFG, impaired glucose tolerance IGT, or T2DM) compared to those with normal glucose tolerance." (PMID 29077742, 2017).
kidney failure (3 papers, 2020 to 2023). An acute or chronic condition that is characterized by the inability of the kidneys to adequately filter the blood. "Among these, higher TXNIP expression was associated with progression to kidney failure (p = 0.004) and with fibrosis (p = 0.002, n = 83)." (PMID 36550108, 2022). "In addition, TXNIP possibly can be targeted to metabolic disease related complications such as cardio-vasculature disease and kidney failure." (PMID 32824669, 2020).
liver disease (3 papers, 2021 to 2024). "However, little is known about the role of TXNIP in LSECs during the development of liver diseases." (PMID 38169654, 2024). "The miR-17, which can suppress NLRP3 inflammasome activation by targeting TXNIP expression, is abundant in AMSC-Exo cargo; this clearly indicates that AMSC-Exo-based therapy may be a promising approach for treating TXNIP/NLRP3 inflammasome-related inflammatory liver diseases." (PMID 34440528, 2021).
lymph node metastasis (3 papers, 2015 to 2024). "In an opposite manner to TXNIP, GDF15 showed a significantly positive correlation with clinical stage and lymph node metastasis in CRC specimens." (PMID 39103698, 2024).
myocardial hypertrophy (3 papers, 2023 to 2024). "Consistently, immunoblotting further demonstrated that NLRP3 deletion attenuated the aggravation of cardiac hypertrophy and fibrosis caused by TXNIP overexpression." (PMID 39604027, 2024). "Another study showed the role of TXNIP as a therapeutic target for the treatment of myocardial hypertrophy by attenuating oxidative stress caused by TXNIP activation through its binding and TXN release." (PMID 37368371, 2023). "It remains unclear whether TXNIP protein exacerbates myocardial hypertrophy and cardiac dysfunction." (PMID 39604027, 2024). "TXNIP inhibitor prevented cardiac hypertrophy by attenuating oxidative stress." (PMID 39604027, 2024).
oral cancer (3 papers, 2020 to 2024). "Knockdown of FOXD1 could significantly inhibite the colony-forming ability of oral cancer cells after radiotherapy and enhance the expression of TXNIP via the JAK-STAT signalling pathway." (PMID 39494294, 2024). "The targeting of FOXD1 might be a good strategy to enhance the radiosensitivity of oral cancer cells via downregulating G3BP2-related pathways and upregulating the TXNIP-associated cellular functions." (PMID 32967107, 2020). "In oral cancer tissues derived from the GSE42734 dataset, we found that the expression of FOXD1 and TXNIP is significantly (p = 0.029) inversed." (PMID 32967107, 2020).
periodontitis (3 papers, 2022 to 2025). An acute or chronic inflammatory process that affects the tissues that surround and support the teeth. "Previous studies have shown that hypoxia is involved in NLRP3 activation and subsequent inflammasome formation by increasing TXNIP expression, and the occurrence of periodontitis is associated with the NRLP3 inflammasome." (PMID 35083332, 2022). "Recent studies have highlighted the role of the ROS/TXNIP/NLRP3 pathway in periodontitis development." (PMID 41298339, 2025). "ROS production in response to LPS also activate the NLRP3 inflammasome by inducing OS‐related proteins like TXNIP and MAVS, which further drive periodontitis progression." (PMID 41298339, 2025). "Recent studies have reported that TXNIP could induce the formation and aggregation of the NLRP3 inflammatory body, leading to dysfunction and injury of periodontal membrane fibroblasts, resulting in periodontitis." (PMID 35083332, 2022).
renal carcinoma (3 papers, 2021 to 2022). A carcinoma arising from the epithelium of the renal parenchyma or the renal pelvis. "The only report on TXNIP and renal cancer evaluated RNA expression data deposited in Cancer Genome Atlas (TCGA) and concluded that decreased expression of TXNIP predicts a poor prognosis." (PMID 34433833, 2021). "Our results showed that UHRF1 inhibited TXNIP expression by enslating HDAC1 to the TXNIP promoter and mediating deacetylation of histone H3K9, thus confirming that UHRF1 may promote tumor progression through epigenetic regulation of TXNIP in renal cancer." (PMID 35656341, 2022).
rheumatoid arthritis (3 papers, 2022 to 2025). A chronic, systemic autoimmune disorder characterized by inflammation in the synovial membranes and articular surfaces. "Similarly, miR-20a acts as a negative regulator of the inflammatory response in rheumatoid arthritis fibroblast-like synoviocytes by targeting TXNIP." (PMID 39220230, 2024).
ulcerative colitis (3 papers, 2022 to 2024). An inflammatory bowel disease involving the mucosal surface of the large intestine and rectum. "Our results confirm that Krüppel‐like factor 4 can positively regulate the expression of TXNIP and regulate the pyroptosis process of ulcerative colitis through the TXNIP/NLRP3 pathway." (PMID 38411328, 2024).
unstable angina pectoris (3 papers, 2018 to 2023). "Our previous studies have shown that TXNIP expression levels in patients with unstable angina pectoris (UAP) were increased compared with controls (CTR)." (PMID 30034557, 2018). "The expression levels of TXNIP were significantly higher in patients with unstable angina pectoris." (PMID 36830671, 2023). "Furthermore, our previous studies have shown that TXNIP expression levels in patients with unstable angina pectoris (UAP) were significantly increased compared with healthy controls (CTR)." (PMID 30034557, 2018).
Acidosis (2 papers, 2010 to 2024). Abnormal acid accumulation or depletion of base. "Lactic acidosis resulted in strong inhibition of glycolysis, glutaminolysis, and altered mitochondrial respiration which reduced cellular ATP content, likely due to increased TXNIP expression and altered NAD+/NADH ratio." (PMID 38195466, 2024).
acute lymphoblastic leukemia (2 papers, 2011 to 2023). Leukemia with an acute onset, characterized by the presence of lymphoblasts in the bone marrow and the peripheral blood. "Additionally, deletion of TXNIP provides strong survival advantage and rescues prednisolone-induced cell death in pre-B Acute Lymphoblastic Leukemia (ALL) cells due to removal of ATP production." (PMID 37794178, 2023). "Furthermore, recent studies have demonstrated that TXNIP gene contains glucocorticoid-responsive elements (GC-RE) and it has been described as prednisolone-responsive gene in acute lymphoblastic leukemia cells." (PMID 21910912, 2011).
age-related macular degeneration (2 papers, 2022 to 2025). Age-related loss of vision in the central portion of the retina (macula), secondary to retinal degeneration. "In a study on age-related macular degeneration (AMD), researchers observed that sustained oxidative stress mediates TXNIP downregulation and disrupts RPE cell function, thereby aggravating AMD." (PMID 36017183, 2022).
alcohol (2 papers, 2019 to 2024). "Other factors known to promote PRMT1 expression include IL4, TXNIP and PDGF18,53,54, however their role in alcohol pathogenesis is not yet evaluated." (PMID 31235809, 2019).
amyotrophic lateral sclerosis (2 papers, 2018 to 2023). Amyotrophic lateral sclerosis (ALS) is a neurodegenerative disease characterized by progressive muscular paralysis reflecting degeneration of motor neurons in the primary motor cortex, corticospinal tracts, brainstem and spinal cord. "(G) RNA-seq data from the Target Amyotrophic Lateral Sclerosis (ALS) dataset of post-mortem lumbar spinal cords were analyzed for DCLK1 (left) and TXNIP (right) counts." (PMID 36951542, 2023).
Arthritis (2 papers, 2023). Inflammation of a joint. "MiRNA-20a targets TXNIP to inhibit the activation of NLRP3, ASC and caspase-1 in adjuvant-induced arthritis FLS and to suppress the secretion of IL-1 and MMP-1." (PMID 37426634, 2023).
autoimmune uveitis (2 papers, 2022 to 2023). An autoimmune form of uveitis (disease). "Corroborating our data, MLT was able to inhibit the differentiation of Th17 cells in an experimental model of necrotizing enterocolitis and, in autoimmune uveitis, MLT suppressed Th17 differentiation through the reactive-oxygen species–TXNIP-HIF1α axis." (PMID 36838425, 2023).
calcification (2 papers, 2022 to 2025). Process by which organic tissue becomes hardened by the physiologic deposit of calcium salts. "In this study, we evaluated the role of TXNIP in galectin-3-induced vascular calcification." (PMID 35771146, 2022).
cervical squamous cell carcinoma (2 papers, 2024 to 2025). A squamous cell carcinoma arising from the cervical epithelium. "SLC2A1, ANO6, and TXNIP are associated with cervical squamous cell carcinoma and may be ferroptosis‐related markers of the disease." (PMID 39526479, 2024). "Meanwhile, SLC2A1, ANO6, and TXNIP are associated with cervical squamous cell carcinoma and may be ferroptosis‐related markers of this disease." (PMID 39526479, 2024). "SLC2A1, ANO6, and TXNIP are associated with cervical squamous cell carcinoma and may serve as ferroptosis‐related markers of the disease." (PMID 39526479, 2024). "The role of TXNIP in ferroptosis, as suggested by its status as a ferroptosis‐related biomarker in cervical squamous cell carcinoma, also warrants investigation." (PMID 40665897, 2025). "In this study, western blot analysis results confirmed that TXNIP expression is downregulated in cervical squamous cell carcinoma tissues." (PMID 39526479, 2024). "Kaplan–Meier analysis showed that the prognosis of patients with cervical squamous cell carcinoma is better than that of patients with downregulated TXNIP." (PMID 39526479, 2024). "Interestingly, TXNIP exhibited a positive correlation with the survival rate and prognosis of patients with cervical squamous cell carcinoma, whereas ANO6 and SLC2A1 showed the opposite trend; both genes were negatively correlated with the survival rate and prognosis of patients." (PMID 39526479, 2024). "Therefore, TXNIP is an anticancer factor in cervical squamous cell carcinoma." (PMID 39526479, 2024).
clear cell renal cell carcinoma (2 papers, 2021 to 2025). "TXNIP has been implicated in ferroptosis in retinal cells, and its downregulation indicates poor prognosis in patients with clear cell renal cell carcinoma." (PMID 34276794, 2021).
coronary atherosclerosis (2 papers, 2016 to 2021). Atherosclerosis of the coronary vasculature. "In this study, we calculated modified Gensini scores and vessels scores, and found the significant correlations of SNP rs7212 and plasma TXNIP levels with the severity of coronary atherosclerosis in a Chinese population." (PMID 27470124, 2016). "Firstly, using a two‐stage case–control design with a total of 1818 CAD patients and 1963 controls, we found that TXNIP SNPs were significantly associated with increased CAD risk and the severity of coronary atherosclerosis in both single locus and cumulative analyses." (PMID 27470124, 2016).
Cushing syndrome (2 papers, 2013 to 2021). Cushing's syndrome (CS) encompasses a group of hormonal disorders caused by prolonged and high exposure levels to glucocorticoids that can be of either endogenous (adrenal cortex production) or exogenous (iatrogenic) origin. "It was reported that the expression of TXNIP was abnormally increased in the bones of patients with Cushing syndrome and also high express in cells or in mice under the treatment of dexamethasone (Dex)." (PMID 34335280, 2021). "Recently, it was found that TXNIP gene highly expressed in the patients with endogenous Cushing’s Syndrome." (PMID 34335280, 2021). "We have previously demonstrated increased bone expression of TXNIP in patients with endogenous Cushing's syndrome (CS), and we hypothesized that TXNIP could contribute to the dysregulated glucose metabolism in CS." (PMID 23691179, 2013).
cystitis (2 papers, 2019 to 2021). Inflammation of the urinary bladder. "In conclusion, we revealed that in rat and cells models, ketamine-associated cystitis was associated with ER stress, apoptosis, TXNIP/NLRP3 aix and ROS." (PMID 31652453, 2019). "In recent years, it was found that NLRP3 inflammation was involved in the progression of cystitis, therefore, targeting the TXNIP/NLRP3 signal axis may be an effective therapeutic target for treating ketamine-associated cystitis." (PMID 31652453, 2019). "The occurrence of oxidative damage in ketamine-induced cystitis resulted in high expression of TXNIP in the bladder, and consistent results were also found in CYP-induced cystitis." (PMID 34804174, 2021). "In order to study the mechanism of LUT improving CYP-induced cystitis, we used western blot to study the expression changes of TXNIP/NLRP3 before and after LUT treatment." (PMID 34804174, 2021). "Our study provides a better understanding ofn the underlying mechanisms of ketamine in ER stress and TXNIP/NLRP3 in vivo and in vitro as well as target strategy for treating ketamine-associated cystitis." (PMID 31652453, 2019).
esophageal cancer (2 papers, 2020 to 2022). A primary or metastatic malignant neoplasm involving the esophagus. "Additionally, mTOR and HDAC inhibitors converge on the TXNIP/thioredoxin pathway and cause oxidative stress and apoptosis in esophageal cancer." (PMID 36661507, 2022). "Studies have also confirmed that TXNIP overexpression can inhibit the proliferation of esophageal cancer cells and increase the therapeutic sensitivity of cisplatin and other chemotherapy drugs used for the treatment of esophageal cancer." (PMID 33194655, 2020).
Glucose intolerance (2 papers, 2020). Glucose intolerance (GI) can be defined as dysglycemia that comprises both prediabetes and diabetes. "PHGDH is previously reported to be involved in the progression of glucose intolerance through serine biosynthesis in mice adipose tissues, while expression of TXNIP is increased in the presence of high glucose, which promotes oxidative stress and β-cell apoptosis." (PMID 32917208, 2020). "TXNIP overexpression but not C247S-mutated (binding site with TRX) TXNIP overexpression in MBH reduces the energy expenditure and causes glucose intolerance, evidence that TXNIP regulates energy homeostasis with TRX in a binding-dependent manner." (PMID 32824669, 2020).
hepatitis B (2 papers, 2021 to 2022). "Some studies claimed that the overexpression of TXNIP strengthens the migration and invasion of HepG2 cells in the transfer of HCC related to hepatitis B, suggesting that HBx-mediated HBV-associated HCC can promote TXNIP expression." (PMID 35450411, 2022).
Hyperoxaluria (2 papers, 2021 to 2024). Increased excretion of oxalates in the urine. "Another study found that in the mouse model of ethylene glycol induced hyperoxaluria, TXNIP, NLRP3, caspase-1, and other genes were significantly upregulated when CaOx crystal deposition began in the kidney of the mice." (PMID 39768161, 2024). "Studies have found that a high expression of TXNIP occurs in the kidney of rats with hyperoxaluria and CaOx kidney stones and induces the activation of NLRP3 inflammasome, showing a strong inflammatory response." (PMID 39768161, 2024). "Additionally, NLRP3 activation contributed to robust ROS production and inflammatory responses via TXNIP in subjects with hyperoxaluria and in a kidney CaOx rat model." (PMID 34512861, 2021).
hypertriglyceridemia (2 papers, 2016 to 2021). A laboratory test result indicating elevated triglyceride concentration in the blood. "The TXNIP protein regulates intra- and extra-cellular reduction-oxidation cycles and genetic variations in this gene have previously been shown to be associated with hypertriglyceridemia in individuals with T2D." (PMID 26798409, 2016).
infarction (2 papers, 2020 to 2025). A localised pathological necrosis of tissue resulting from obstruction of the blood supply usually by a thrombus, an embolus, or vascular torsion. "M2‐Exosome promoted miR‐148a expression thus ameliorated myocardial pyroptosis, cardiac injuries, myocardial Ca2+ overload and infarction through TXNIP/TLR4/MyD88/NF‐κB/NLRP3 signalling pathway in I/R rats." (PMID 39929748, 2025).
Infertility (2 papers, 2014 to 2026). "Hyperandrogenism and elevated thioredoxin-interacting protein (TXNIP) are potential causes of infertility in women with polycystic ovary syndrome (PCOS)." (PMID 41934343, 2026).
insulinoma (2 papers, 2014 to 2021). "Unlike a strong induction of TXNIP/TBP-2 by high glucose in insulinoma cells, the level of TXNIP/TBP2 in SH-SY5Y cells was constitutively high and was not induced further by high glucose." (PMID 24624334, 2014).
intervertebral disc degeneration (2 papers, 2021 to 2022). "For instance, Morin mitigates thioredoxin-interacting protein (TXNIP)/NLRP3/Caspase-1 signaling pathway-mediated pyroptosis in nucleus pulposus cells and ameliorates intervertebral disc degeneration." (PMID 34366853, 2021).
ischemic disease (2 papers, 2021 to 2022). Lack of blood supply to an area of the body, resulting in impairment of tissue oxygenation. "TXNIP is a potential biomarker in cardiovascular and ischemic diseases but also a novel identified target for preventive and curative medicine." (PMID 33567593, 2021). "The mechanisms involved are specified and TXNIP is identified as a potential target for preventive and curative medicine in cardiovascular and ischemic diseases." (PMID 33567593, 2021). "After an overview in TXNIP involvement in oxidative stress, inflammation and metabolism, the remainder of this review presents the clues used to define TXNIP as a new marker at the genetic, blood, or ischemic site level in the context of cardiovascular and ischemic diseases." (PMID 33567593, 2021).
Knee Osteoarthritis (2 papers, 2021 to 2024). "Evidence has also indicated that kaempferol can improve the oxidative and inflammatory damage of knee osteoarthritis rat chondrocytes by inhibiting the ROS/TXNIP pathway, thereby regulating the levels of oxidative markers and inflammatory factors." (PMID 39221164, 2024).
Laron syndrome (2 papers, 2022 to 2024). Laron syndrome is a congenital disorder characterized by marked short stature associated with normal or high serum growth hormone (GH) and low serum insulin-like growth factor-1 (IGF-I) levels which fail to rise after exogenous GH administration. "Our previous study on Laron syndrome, a rare congenital IGF1 deficiency, identified a novel link between the IGF1 signaling pathway and TXNIP." (PMID 36291127, 2022).